CTSB (cathepsin B)
Diseases named in the same sentence as CTSB in open-access papers (continued):
Sharing a sentence is not in itself a finding about the gene and the disease.
cervical carcinoma (8 papers, 2009 to 2025). A carcinoma arising from either the exocervical squamous epithelium or the endocervical glandular epithelium. "There are also studies demonstrating that quercetin downregulates cathepsin B in cervical cancer cells and in aged Institute of Cancer Research (ICR) mice." (PMID 40566630, 2025). "The RNAseq data also revealed significantly poorer survival of patients with cervical cancer when related to high CTSB and CTSZ expression." (PMID 31748500, 2019). "CTSB expression in invasive tumors was positively correlated with lymphatic metastasis, suggesting that CTSB contributes to cervical cancer development." (PMID 27031837, 2016). "LMP induced by TNF-alpha has been shown to be dependent on CTSB and the cationic amphiphilic drug resveratrol has been shown to induce LMP in cervical cancer cells that are dependent on autophagy and CTSL." (PMID 33919392, 2021). "Under normal conditions, both cathepsin B and L are partly co-localized with IGF2R in cervical cancer cells." (PMID 31748500, 2019).
cognitive decline (8 papers, 2020 to 2025). "Cathepsin B, as implicated in the previous section, is another serum marker elevated in both periodontal disease and AD, and it is strongly correlated with cognitive decline." (PMID 40559320, 2025). "Studies suggest that the neuroinflammation of P. gingivalis LPS is primarily dependent on cathepsin B, and this could be targeted to prevent AD cognitive decline in periodontal disease patients." (PMID 40559320, 2025). "Physical exercise seems to modulate several factors relevant for the connection between skeletal muscle and the brain, such as neurotrophins (e.g., BDNF and plasma Cathepsin B (CTSB) levels) and oxidative stress parameters (e.g., lipid oxidation markers) that help to mitigate cognitive decline." (PMID 35547585, 2022). "Importantly, CTSB deletion in aged wild-type mice has been shown to reduce oxidative stress, inflammation, and cognitive decline, indicating that CTSB could be a viable target for anti-aging and cerebrovascular protective therapies [1094]." (PMID 40407975, 2025).
coronary heart disease (8 papers, 2021 to 2024). "In a 10‐year follow‐up of the CLARICOR trial, it was observed that in patients with stable coronary heart disease, serum CTSB levels were found to be associated with high risk for cardiovascular events." (PMID 39248527, 2024). "In patients with stable coronary heart disease, CTSB is associated with high risk for cardiovascular events, arterial stiffening and atherosclerotic vascular disease." (PMID 37202785, 2023). "Studies conducted in vitro or in vivo models have revealed that over-expression of CTSB/D can contribute to the formation of arterial plaques and increase the risk of coronary artery disease." (PMID 33964876, 2021). "The CLARICOR study found that serum CTSB was associated with an increased risk of cardiovascular events in patients with stable coronary heart disease and higher cathepsin activity along with an M2 macrophage phenotype was observed in carotid plaques from symptomatic patients." (PMID 33460396, 2021). "The long‐term follow‐up results indicated that elevated circulating CTSB levels were associated with an increased risk of cardiovascular events, suggesting its potential utility as a risk marker for predicting adverse cardiovascular outcomes in patients with stable coronary heart disease." (PMID 39248527, 2024). "In a long‐term follow‐up subclinical trial known as CLARICOR43 (effect of clarithromycin versus placebo on mortality and morbidity in patients with ischaemic heart disease), serum CTSB levels were assessed in 4372 stable coronary heart disease patients." (PMID 39248527, 2024). "The expression levels of members of the cathepsin family (CTSD/CTSB) were up-regulated in patients with coronary heart disease." (PMID 36959587, 2023). "In this study, to better understand the mechanism of CTSD/CTSB in sudden coronary heart disease death, we also analyzed the TF-mRNA-miRNA relationship to obtain the co-regulatory network." (PMID 33964876, 2021). "This study compared the effects of linear (LP) and nonlinear (NLP) training periodization on cognitive functions, neurotrophic biomarkers [plasma brain-derived neurotrophic factor (BDNF), insulin-like growth factor-1 (IGF-1)], and cathepsin-B in patients with coronary artery disease (CAD)." (PMID 38961824, 2024). "However, the relationship between CTSB/D and coronary heart disease in autophagy regulation remains unclear." (PMID 33964876, 2021). "As expected, independent studies showed that patients with coronary artery disease had elevated levels of plasma CTSK, CTSS, CTSL, and CTSB compared to healthy individuals." (PMID 37202785, 2023).
lung fibrosis (8 papers, 2008 to 2025). "Functional role of EVs cathepsin was previously established when presence of CTSB in R3/1 exosomes, stimulated by oxidative stress, promoted RAGE protein expression in recipient cells that is associated with pulmonary fibrosis." (PMID 32466345, 2020). "Current data are in sharp contrast to previous analysis carried on human BALF from patients with idiopathic pulmonary fibrosis, for which the level of cathepsin B remained unchanged while cystatin C was significantly increased." (PMID 27658724, 2016). "In terms of the toxicology mechanisms involved in rare earth pneumoconiosis, we have demonstrated a NLRP3 inflammasome pathway in macrophage-like cells responsible for REO-induced lung fibrosis by eliciting lysosomal damages, cathepsin B release, and IL-1β release." (PMID 33902647, 2021).
Stroke (8 papers, 2012 to 2025). Sudden impairment of blood flow to a part of the brain due to occlusion or rupture of an artery to the brain. "Therefore, the serum level of CTSB and HIF-1α in stroke patients remains inconclusive and their association with MBE after stroke needs further investigation." (PMID 34493232, 2021). "Furthermore, treatment with a cathepsin B inhibitor in vivo is neuroprotective following stroke." (PMID 23024646, 2012).
cholangiocarcinoma (7 papers, 2014 to 2024). A carcinoma that arises from the intrahepatic biliary tree (intrahepatic cholangiocarcinoma) or from the junction, or adjacent to the junction, of the right and left hepatic ducts (hilar cholangiocarcinoma). "Reduced cell proliferation was observed when the CTSB gene was inhibited in cholangiocarcinoma cells." (PMID 35923240, 2022). "Redistribution of the cathepsin B from lysosomes to the cytosol in cholangiocarcinoma cells was induced by TRAIL and contributed significantly to apoptosis." (PMID 25310712, 2014). "MiR-637 blocks the migration of cholangiocarcinoma cells by interfering with CTSB." (PMID 32399056, 2020). "In the human cholangiocarcinoma cell line QBC939, CTSB expression inhibited by mir-637 can decrease proliferation ability and promote apoptosis." (PMID 37576397, 2023). "In the digestive tract, CTSB was overexpressed in colon adenocarcinoma (COAD), esophageal carcinoma (ESCA), pancreatic adenocarcinoma (PAAD), rectum adenocarcinoma (READ), and stomach adenocarcinoma (STAD) rather than cholangiocarcinoma and liver hepatocellular carcinoma." (PMID 35155389, 2022).
depression (7 papers, 2020 to 2025). "CTSB has been linked to both protective and deleterious effects in the context of anxiety and depression." (PMID 41463031, 2025). "Assessment of anxiety-related and depression-like behaviours in cathepsin B-deficient mice revealed an increase in depression-like behaviours in females." (PMID 37958596, 2023). "Accordingly, loss of CTSB expression resulted in an increase in anxiety-like and depression-like behavior." (PMID 32793006, 2020). "Transcriptome analysis of inbred mouse lines selected for low or high anxiety-related behaviour with depression-like behaviour revealed that cathepsin B is responsible for low anxiety in female mice." (PMID 37958596, 2023). "Serum interleukin‐6 (IL‐6), irisin, brain‐derived neurotrophic factor (BDNF), kynurenine, and cathepsin B were analyzed and compared to surrogates of depression and quality of life." (PMID 33655551, 2021). "Transcriptome analysis of inbred mouse lines, selecting for low or high anxiety-related behavior with depression-like behavior, revealed higher CTSB levels in low anxiety mice." (PMID 32793006, 2020). "While some studies indicate that CTSB promotes neuroinflammation via activated microglia, which typically exacerbates depression-like behaviors, other findings suggest that high levels of CTSB may protect against these disorders." (PMID 41463031, 2025). "We, therefore, hypothesize that MT alleviates chronic stress-induced hippocampal microglia pyroptosis and subsequent depression-like behaviors by inhibiting the Cathepsin B/NLRP3 signaling pathway." (PMID 38538614, 2024). "Thus, this study investigated the impact of regular leisure-time physical activity on cognitive function (plasma BDNF, NGF, and cathepsin B) and menopausal parameters (the climacterium, depression, and cognitive tests) in obese, middle-aged women." (PMID 33233633, 2020). "In contrast to CTSB, CTSC appears to play a more uniformly detrimental role in the development of depression and anxiety." (PMID 41463031, 2025). "Therefore, MT can alleviate hippocampal pyroptosis by inhibiting Cathepsin B/NLRP3 signaling pathway, thereby improving the depression-like behaviors of chronic stress rats." (PMID 38538614, 2024). "However, it is unclear whether MT improves microglia pyroptosis by inhibiting the Cathepsin B/NLRP3 pathway, thereby alleviating hippocampal injury and subsequent depression-like behaviors." (PMID 38538614, 2024). "Nevertheless, the relationship between regular physical activity, cognitive factors (plasma nerve growth factor (NGF), brain-derived neurotrophic factor (BDNF), and cathepsin B levels), and psychological parameters (the climacterium, depression, and cognition) has not yet been investigated." (PMID 33233633, 2020).
esophageal cancer (7 papers, 2016 to 2024). A primary or metastatic malignant neoplasm involving the esophagus. "In esophageal cancer, the cystatin C /CTSB ratio was significantly lower in the esophageal cancer group than in the control group and significantly correlated with the T stage and lymph node metastasis." (PMID 37576397, 2023). "Cathepsin B is a potential target for detecting esophageal cancer because it is expressed at low levels in the normal esophageal mucosa but is significantly overexpressed in esophageal cancer." (PMID 28402938, 2017). "Conversely, in muscle biopsies of esophageal cancer patients increased LC3B-II/LC3B-I ratio and unchanged p62 protein level paralleled with increased cathepsin B and L activity." (PMID 27459917, 2016).
Hepatic steatosis (7 papers, 2007 to 2025). Steatosis is a term used to denote lipid accumulation within hepatocytes. "In contrast, in rodent models it has been reported that whole-body pharmacological and genetic inactivation of CTSB protected against the development of hepatic steatosis and whole-body insulin resistance." (PMID 32486882, 2020). "Inactivation of cathepsin B in a dietary murine model of NAFLD prevented the development of hepatic steatosis." (PMID 31060228, 2019). "Moreover, in NAFLD patients, hepatic steatosis showed a decreased expression of cathepsin B, D, and L proteases leading to inhibition of autophagic proteolysis." (PMID 33976943, 2021). "The study further pointed out that autosomal and liver cathepsin B and L proteinase activities were suppressed in ob/ob mice, indicating that hepatic steatosis inhibited autophagic proteolysis via impairment of autophagosomal acidification and cathepsin downregulation." (PMID 33976943, 2021). "In hepatic steatosis (see Section 5.4), overabundant palmitate together with pro-apoptotic Bax can permeabilize the lysosomal membrane, followed by the release of the lysosomal cysteine protease cathepsin B into the cytosol." (PMID 33143278, 2020). "Moreover, they demonstrated that leakage of cathepsin B into the cytosol occurs in human NAFLD, whereas inhibition of cathepsin B produces protection against diet-induced fatty liver disease in mice." (PMID 37111122, 2023).
myeloma (7 papers, 2008 to 2024). "CTSB has a prominent function in mediating apoptosis potentiated by sodium butyrate (an HDACi), and doxorubicin combinations in myeloma." (PMID 28881816, 2017). "Previous reports had shown that supramitogenic doses of ATGs led to apoptosis of peripheral blood lymphocytes from healthy donors and myeloma cells depending on caspases, particularly on Cathepsin B." (PMID 22479483, 2012). "Cathepsin B has a prominent function in mediating apoptosis potentiated by HDACi and doxorubicin combinations in myeloma." (PMID 21364585, 2011). "In this study, we identified a critical role for cathepsin B in mediating the potentiation of apoptosis in myeloma cells by HDACi and doxorubicin combinations at their IC50 concentrations." (PMID 21364585, 2011). "CTSB activation can enhance HDACi- and adriamycin-induced apoptosis in myeloma cells, which may be related to the nuclear translocation of apoptosis-inducing factor (AIF)." (PMID 37576397, 2023).
oral squamous cell carcinoma (7 papers, 2016 to 2026). "The expression of CTSB has been reported to be increased along with the cancerization in oral squamous cell carcinoma, which is also positively associated with highly invasive and metastatic phenotypes." (PMID 29925404, 2018). "This systematic review included 10 relevant studies that focused on various biomarkers associated with oral squamous cell carcinoma (OSCC), including Ki67, HSP60, Survivin, PD-L1, E-cadherin, Cathepsin B and Stathmin." (PMID 40818120, 2026). "This comprehensive review delves into the intricate landscape of oral squamous cell carcinoma (OSCC) by examining the role of cathepsin B expression in its pathogenesis." (PMID 38500921, 2024). "The main purpose of this study was to analyze CTSB expression in oral squamous cell carcinoma (OSCC) and its correlation with patient prognosis." (PMID 27031837, 2016). "The expression of cathepsin B has been recently reported in oral cavity SCC." (PMID 28775982, 2017).
osteoarthritis (7 papers, 2011 to 2025). A noninflammatory degenerative joint disease occurring chiefly in older persons, characterized by degeneration of the articular cartilage, hypertrophy of bone at the margins and changes in the synovial membrane. "We shall explore the regulation mechanism of the miR-140-5p/CTSB/NLRP3 axis in osteoarthritis clinically in our future endeavors." (PMID 34565303, 2021). "Cathepsin B is elevated in in vitro models of osteoarthritis and promotes early embryonic patterning in zebrafish via BMP signaling, but no jaw phenotypes were noted in mutants." (PMID 28715414, 2017). "In the peripheral inflammatory conditions of RA and osteoarthritis (OA) synovial cells and chondrocytes have increased cathepsin B mRNA levels and cathepsin B protein secretion relative to controls." (PMID 26388830, 2015). "Severe conditions of excessive cathepsin B-mediated degradation of extracellular matrix (ECM) components, as it is observed in osteoarthritis, is believed to arise when cathepsin B is secreted into the extracellular space in a non-regulated manner." (PMID 21835049, 2011).
pancreatic ductal adenocarcinoma (7 papers, 1994 to 2026). An infiltrating adenocarcinoma that arises from the epithelial cells of the pancreas. "Among them, cathepsin B, L, and S have been predominantly associated with tumor progression in various cancer entities, including pancreatic ductal adenocarcinoma." (PMID 32927704, 2020). "The high expression of CSTB in pancreatic ductal adenocarcinoma reduces the inhibition of CTSB, thereby acting as a tumor-promoting factor." (PMID 39996856, 2025). "In pancreatic ductal adenocarcinoma, CSTB competes with cystatin C (CSTC) to bind cathepsin B (CTSB), but CSTC has stronger cathepsin inhibitory activity." (PMID 39996856, 2025). "Cystatin 6 (CST6) is overexpressed in pancreatic ductal adenocarcinoma (PDAC) cells and can stimulate PDAC cell growth by reducing the activity of intracellular cathepsin B." (PMID 33173782, 2020).